PPARA (peroxisome proliferator activated receptor alpha)
Diseases named in the same sentence as PPARA in open-access papers (continued):
Sharing a sentence is not in itself a finding about the gene and the disease.
steatosis (continued). "Most importantly, authors also demonstrated that PPARα restoration is able to promote transcriptional activation of several genes involved in lipid metabolism, such as CPT1A and SLC27A, thus leading to steatosis improvement." (PMID 34299336, 2021). "In vitro and in vivo studies in mice observed that miR-34a specifically targets PPARα and Sirtuin 1 (SIRT1), thereby suppressing FAs catabolism and eliciting steatosis." (PMID 34299336, 2021). "Studies of PPARA liver expression in mice with steatosis in response to a high-fat diet show sex-differences: PPARA expression is increased in male rats, and FASN, which is directly downstream of PPARA, is also increased." (PMID 34861817, 2021). "Lactobacillus plantarum AR113 and Lactobacillus casei pWQH01 with high bile salt hydrolase active can improve steatosis by reducing the expression of SREBP-1c, ACC, FAS and TNF-α and increasing the expression of AMPK and PPARα in vitro." (PMID 33281535, 2020). "In this study, we observed the beneficial effect of co-treatment with a PPARα agonist and metformin on the progression of NAFLD in three major manifestations of liver disease, that is, steatosis, inflammation, and fibrosis." (PMID 33177546, 2020). "The protective effect of PPARα was further demonstrated by treating fibrotic APOE2KI811A mice with the PPARα agonist fenofibrate, which protected mice from NASH by reducing both steatosis and hepatic macrophage accumulation." (PMID 32660130, 2020). "The activity regulation of PPARα, PPARγ, and RXRα in mouse models of NASH was instead more representative of their activity in human livers with simple steatosis." (PMID 32660130, 2020). "In particular, the concurrent activation of hepatic Pparα and inhibition of Pparγ by supplemental nitrate suggest a potential application for the prevention and treatment of HFD-induced steatosis." (PMID 32001953, 2020). "Several distinct major nodes are apparent including PPARA downregulated in steatotic grafts and SERPINE1 upregulated in steatosis compared to controls." (PMID 31114547, 2019). "As the regulated genes of lipolysis, PPARα, ACOX and CPT1 exert important roles on keeping lipid away from deposition and steatosis." (PMID 30709407, 2019). "Silencing of miR-34a restored the expression of SIRT1 and Peroxisome proliferator-activated receptor α (PPARα), resulting in activation of PPARα downstream genes, such as AMPK and Hydroxymethylglutaryl-CoA Reductase (HMGCR), thus ameliorating steatosis." (PMID 30544653, 2018). "In contrast, hepatic PPARα, PPARβ/δ, Foxa2, and circadian clock BMAL1 exert anti-steatosis action by promoting fatty acid β oxidation." (PMID 30013137, 2018). "Analogous pathways are affected by Foxa2 binding in Zmpste24‐deficient livers as in older hepatocytes, including activation of genes regulated by PPARα and LXR, factors that contribute to steatosis in older livers." (PMID 29484800, 2018). "To further explore the biological impact of PPARα-mediated gene regulation in response to lipid loading, we monitored metabolic fluxes towards TAG as a representative endpoint in steatosis." (PMID 30131870, 2018). "As recently published by Jang and colleagues, endogenous hepatic plasmalogens appear to be involved in fatty acid metabolism and inhibit steatosis and NASH progression through PPARα-dependent signaling." (PMID 29883377, 2018). "Although both miR-21 ablation or OCA supplementation resulted in a modest decrease in steatosis, the dual activation of PPARα and FXR resulted in markedly reduced lipid accumulation, diffused microvesicular steatosis and a lipidosis score of 2.33 (P<0.05)." (PMID 28406477, 2017). "Second, direct interaction between LPIN1 and transcription factors (PPARα, PGC-1α) amplifies the hepatic PGC-1α/PPARα signaling in steatosis-related gene expression." (PMID 28717649, 2017). "Our results showed that steatosis and inflammation progressively increase with time after MCD feeding, in parallel with a progressive decrease in PPARα." (PMID 28406477, 2017).
steatosis (continued). "Corroborating the results obtained with the animal models of NASH, expression of miR-21 in the liver of NAFLD patients significantly increased from steatosis to NASH (P<0.01), with a concomitant decrease in PPARα expression (P<0.01)." (PMID 28406477, 2017). "Wy14,643, a PPARα gene agonist, improved steatosis and ballooning in diabetic NASH model mice, and a dual PPARα/δ agonist exerted liver-protective effects on steatosis, inflammation, and fibrosis in several rodent models." (PMID 27723801, 2016). "However, agonists of PPARα administered to foz/foz mice (rendered diabetic by feeding with a HF diet) failed to resolve liver inflammation although other histological parameters, including steatosis, hepatocytes ballooning and neutrophils/macrophages recruitment, were improved." (PMID 23024649, 2012). "PPARα also increases expression of fatty acid transporters, promoting fatty acid influx and leading to further PPARα activation by acting as PPAR ligands; this helps to explain the role of PPARα in HCV-induced steatosis in the animal model." (PMID 22966221, 2012). "Induction of PPARα by WY14643 treatment for 2 weeks attenuated ethanol induced liver injury, as evidenced by diminished histological steatosis and inflammatory response, improved hepatocyte ultrastructure, as well as decreased serum ALT and AST levels." (PMID 22208561, 2011). "In contrast to the extensive data on the role of rodent CYP4A gene in animal models of steatosis and steatohepatitis, little is known about how the human CYP4A11 gene is controlled by PPARα agonists and its functional role in NAFLD or NASH." (PMID 20300478, 2009). "Our study also showed that a chronic activation of PPARα improves steatosis independent of FGF21 induction." (PMID 40815899, 2025). "In pathological conditions, the PPARα level increases, determining the activation of acyl-CoA-binding domain-containing 3 (ACBD3), CPT2, and of fatty acid transport protein SLC27A, and ultimately reducing steatosis." (PMID 41226441, 2025). "Indeed, Nrf2, as it is also an antioxidant and anti-inflammatory agent, can suppress hepatic lipogenesis and steatosis and stimulate FA oxidation by improving mitochondrial biogenesis, inhibiting SREBP1, and upregulating PPARα." (PMID 38004149, 2023). "This direct anti-steatosis effect might be explained by downregulating LDL, activating peroxisome proliferator-activated receptor alpha (PPARα) alongside increased β-oxidation, but further research is warranted to identify involved pathways." (PMID 36502575, 2023). "Furthermore, CBD improved alcohol-induced hepatic metabolic dysregulation and steatosis by restoring changes in hepatic expression of ACC-1, FASN, PPARα, MCAD, ADIPOR-1, and mCPT-1." (PMID 35644678, 2022). "Similarly, in subjects with non-alcoholic steatohepatitis (NASH), hepatic PPARα expression declined with the development of NASH features and was negatively correlated with the severity of steatosis, hepatocyte ballooning or fibrosis." (PMID 36139455, 2022). "Inhibition of miR-34a could alleviate steatosis and suppress lipid accumulation in the mouse NAFLD model by specifically targeting hepatic PPARα and SIRT1." (PMID 35052597, 2021). "While the expression of other candidates, including RORA, RORC, and THRB, remained unchanged, that of PPARA significantly decreased as NAFLD progressed to steatosis and NASH, and showed a negative correlation with that of MIR20B." (PMID 34964438, 2021). "In contrast, gene expression patterns in the high steatosis lines indicate impaired fasting responses with low levels of PPARα in S08 cells and no changes in PGC1α after OA induction in S12, S11 and S08 cells." (PMID 33372064, 2021). "Fibrates act as PPARα agonists and they has been evaluated for NAFLD treatment: it has been showed a positive effect on transaminase and GGT, but no significant changes were observed in histologically assessed steatosis, inflammation, and fibrosis." (PMID 31703268, 2019).
steatosis (continued). "In this context, activation of PPAR signaling would offer a counteracting mechanism to deactivate fibrogenic stellate cells; in fact, PPARA is a known transcriptional regulator with reported protective roles against steatosis in hepatocytes." (PMID 29868123, 2018). "In this study, the patients with steatosis had lower levels of PPARα, ACOX1 and CPT1A than the ones without steatosis." (PMID 29022907, 2017). "The administration of PPARα agonists have been shown to attenuate MCD-induced hepatic TG accumulation, and to upregulate the mRNA of liver FABP and β-oxidation enzymes, thereby reducing hepatic TG and preventing steatosis in mice." (PMID 28594915, 2017). "Furthermore, CBD improved alcohol-induced hepatic metabolic dysregulation and steatosis by restoring changes in hepatic mRNA or protein expression of ACC-1, FASN, PPARα, MCAD, ADIPOR-1, and mCPT-1." (PMID 28935932, 2017). "We performed histological scoring and found that, in the fed state, steatosis was only detectable in Pparα−/− mice, not in wild-type mice, regardless of the diet." (PMID 27669233, 2016). "Therefore, based on the importance of PPARα in systemic lipid homeostasis and α-ESA as a PPARα agonist, our objective was to investigate the role of PPARα in BMSO-mediated anti-steatosis and anti-adiposity functions." (PMID 27973445, 2016). "Our results suggest that hypoglycaemia and steatosis occur in Pparα−/− mice regardless of the composition of their diet." (PMID 27669233, 2016). "Interestingly, PPARαhep−/− mice developed steatosis and hypercholesterolemia with aging similarly to whole body PPARα−/− mice but did not become obese nor hyperglycaemic, confirming that hepatocytic PPARα deletion by itself is a primary cause of liver steatosis." (PMID 28115925, 2016). "Beinga central regulator of triglyceride homeostasis and mediating hepatocarcinogenesis in rodents, not surprisingly PPARα, contributes to steatosis and HCC induced by hepatitis C virus (HCV) in rodent models." (PMID 23028383, 2012). "In particular, we noted increased liver TG levels and steatosis with TRI exposure in Pparα-null and hPPARα mice, but not in mPPARα mice." (PMID 20709644, 2010). "Activation of PPARα and peroxisomal proliferation might contribute to the increased liver weight in c9, t11-CLA-treated mice, steatosis also playing a role, at least in the case of t10, c12-CLA." (PMID 15642120, 2005). "Improved Lipid Metabolism: The upregulation of peroxisome proliferator-activated receptor alpha (PPARα) and lipoprotein lipase (LPL) expression enhances fatty acid oxidation and lipid clearance, while reduced fatty acid synthase (FAS) expression decreases lipogenesis and steatosis." (PMID 40136563, 2025). "Additionally, the results of AH patients, NIAAA, and ALD mouse models have indicated that excessive alcohol consumption inhibits the ADRB2/SIRT1/PGC-1α/PPARα pathway, leading to elevated levels of oxidative stress and cytokines such as CCL2, CXCL8, and CXCL10, accompanied by hepatic steatosis." (PMID 39640486, 2024). "We also provided an alternative mechanism by which ATL I binds with SIRT6 to activate PPARα and its target genes and suppresses inflammatory factor release by attenuating NFκB-mediated NLRP3 inflammasome formation, which, together, attenuate hepatic inflammation and steatosis." (PMID 36558977, 2022). "In addition, our previous study showed THC increased lipolysis, upregulated PPARα and CPT-1 in oleic acid-induced steatosis HepG2 cells, which may stimulate fatty acid oxidation." (PMID 34960104, 2021). "In addition, the modest reduction in PPARα combined with those of CPT1α and MCAD protein levels in the NAFL group suggest that a decrease in fatty acid beta-oxidation could contribute to steatosis in this CD-HFD model." (PMID 32486073, 2020). "Thus, simultaneous activation of Pparα and inhibition of Pparγ through nitrate supplementation may be a target for the prevention and treatment of HFD-induced steatosis." (PMID 32001953, 2020).
steatosis (continued). "Importantly, although Pparα-null mice develop steatosis, they do not exhibit reduced glucose tolerance compared to WT mice." (PMID 32300166, 2020). "Thus, simultaneous activity at multiple receptors triggering different sub-pathways within the steatosis AOP, for example activation of PXR and inhibition of PPARα, possibly play a key role for the high biological activity of azole compounds with respect to triglyceride accumulation." (PMID 32403288, 2020). "Suggestive of a protective function, mice lacking PPARα expression exhibit more severe steatosis." (PMID 32660130, 2020). "Since PPARα is expressed and active in many organs, it is possible that the absence of PPARα in these organs might contribute to the development of fasting-induced steatosis." (PMID 29954129, 2018). "Therefore, we think miR-34a-mediated PPARα regulation and SIRT1-AMPK pathway may be two separate regulatory mechanisms in steatosis, but there was a certain link between them, beacause both of them stimulated AMPK signaling." (PMID 26330104, 2015). "This suggests that the human PPARα insertion did not restore proper lipid regulation in the liver, but instead resulted in receptor overexpression that exacerbated lipid dysregulation by increasing TG storage and steatosis." (PMID 20709644, 2010). "Steatosis, decreased hepatic peroxisome abundance, and impaired fatty acid oxidation are observed in rats chronically undernourished by a low-protein diet; these abnormalities are partially ameliorated by a PPARα agonist, suggesting a lack of PPARα signaling in chronic undernutrition." (PMID 35419389, 2022). "However, there is a possibility that the improvement in steatosis by FXR-ligands are due to not only to inhibition of lipogenesis but also to enhancement of lipolysis, because there is molecular crosstalk between the FXR and peroxisome proliferator-activated receptor-α (PPARα; NR1C1)." (PMID 30936623, 2019). "Moreover, these mice displayed increased levels of nuclear SREPB-1c, while PPARα, phospho-AMP kinase and 3-keto-acyl-CoA thiolase were significantly decreased, suggesting that these alterations in fatty acid metabolism could be part of the mechanism by which AZT induces steatosis." (PMID 35052872, 2022). "Both IHC analysis and western blot assays showed the proteins of CYP7A1, PGC-1α, PPARα, CPT1A and ACOX1 were decreased in livers tissues from patients with steatosis when compared with ones without steatosis." (PMID 29022907, 2017). "In addition, VD did not exert an anti-steatosis effect via the regulation of lipid uptake and β-oxidation in the presence of the MK886 PPARα inhibitor." (PMID 37033263, 2023). "Although the BMSO-mediated anti-steatosis effect disappeared without functional PPARα, hepatic PPARα activation by BMSO in this study was not as prominent as expected, since only enzyme activity, but not mRNA of the PPARα target gene, was increased by BMSO in WD mice." (PMID 27973445, 2016).
atherosclerosis (247 papers, 2005 to 2026). A disease characterized by the build-up of fatty material and calcium deposition in the arterial wall resulting in partial or complete occlusion of the arterial lumen. "Subsequent administration of a miR-27b-3p mimic induced inflammation and atherosclerosis in apolipoprotein E deficient (ApoE−/−) mice, whereas PPARα overexpression counteracted these effects and provided protection against atherosclerosis." (PMID 39327610, 2024). "Peroxisome proliferator-activated receptor-α (PPARα) has been associated with atherosclerosis, but its role in T2DM is less clear." (PMID 36142760, 2022). "Some complications that resulted from hyperglycemia, including atherosclerosis, retinopathy, and diabetic nephropathy, are associated with PPARα function." (PMID 36589809, 2022). "Homocysteine-mediated DNA methylation of PPARα and PPARγ participates in the pathogenic mechanism of atherosclerosis." (PMID 34362460, 2021). "These direct atheroprotective together with the lipid lowering effects are largely responsible for the observation that pharmacological PPARα activators cause an inhibition of atherosclerosis development." (PMID 22129452, 2011). "For example, the transcription of Per2 is regulated by RXRα, the ligand of PPARα, which regulates lipid and lipoprotein metabolism, and inflammation, major risk factors for atherosclerosis." (PMID 20040117, 2009). "The in vivo significance of macrophage PPARα is illustrated by enhanced atherosclerosis in low-density lipoprotein receptor-deficient mice transplanted with PPARα−/− bone marrow, which is due to an increased inflammatory response of macrophages." (PMID 18615187, 2008). "For example, wefound that treatment with the dual PPARα/γ agonist, compound 3q, was associated with amarked increase in atherosclerosis in control apoE KO mice, while PPARγ and α agonistsused alone in this model were protective." (PMID 18288280, 2008). "Its role in promoting atherosclerosis initiation and development may be associated with regulation of TG metabolism via the PPARα pathway." (PMID 41476864, 2025). "Similarly, heart-protecting musk pill (麝香护心丸) is found to attenuate atherosclerosis partially via activating PPARα/CPT-1α signaling pathway in ApoE-deficient mice." (PMID 38699583, 2024). "However, Ascophyllum nodosum-derived fucoidan is found to inhibit the expression of PPARγ and elevate the expression of PPARα, thereby attenuating hyperlipidemia and atherosclerosis in ApoE-deficient mice." (PMID 38699583, 2024). "The authors suggested that reduced fatty acid oxidation in blood vessel walls of Pparα deficient mice could ultimately promote reduced superoxide production and thus decrease atherosclerosis and blood pressure." (PMID 26649033, 2015). "Weight loss increases Pparα and Pparγ, associated with a decrease in atherosclerosis." (PMID 23620818, 2013). "Peroxisome proliferator-activated receptor alpha (PPARα) regulates genes involved in lipid metabolism, homeostasis and inflammation, in response to fatty acids, and fibrates, making it a candidate gene for risk of dyslipidaemia, atherosclerosis, and coronary artery disease." (PMID 22347658, 2011). "Together, these data identify OEA as a modulator of Treg differentiation and activity and support its potential as a PPARα-dependent strategy to promote plaque regression and immune homeostasis in atherosclerosis." (PMID 42248455, 2026). "UCP1 is activated by PPARα and PPARγ has been shown to inhibit atherosclerosis by reducing vascular inflammation." (PMID 40753563, 2025). "The effects of the activation or deletion of PPARα, PPARδ/β, and PPARγ, especially in macrophages, on atherosclerosis have been studied in animal models." (PMID 40305368, 2025).